IL6 (interleukin 6)
Diseases named in the same sentence as IL6 in open-access papers (continued):
Sharing a sentence is not in itself a finding about the gene and the disease.
gout (continued). "Compared with WT mice, St2-/- mice showed significantly reduced expression of IL-1β, IL-6, IL-13, CCL11, G-CSF, CXCL1, CCL2 and CCL3 proteins in ankle tissues, suggesting St2-/- mice showed generally attenuated inflammatory response during gout." (PMID 33204337, 2020). "Conversely, IL-1α, IL-6, IL-12(p40), G-CSF, MCP-1, and TNF-α, which could be induced by gouty arthritis, were significantly reduced by Simiao decoction and febuxostat." (PMID 32670069, 2020). "Here, we show that caspase-11−/− mice and their derived macrophages produce significantly reduced levels of gout-specific cytokines including IL-1β, TNFα, IL-6, and KC, while others like IFNγ and IL-12p70 are not altered." (PMID 31803174, 2019). "Chlorogenic acid has been shown to exert anti-gout activity as well as improvement on hyperuricemia and inflammation by inhibiting the XOD activity, serum UA levels, and production of proinflammatory cytokines (e.g. IL-1β and IL-6)." (PMID 30621705, 2019). "The increased concentration of plasma ox-LDL might be related to the increase of IL-6 and TNF-α leading to increased generation of peroxides in gout patients." (PMID 24068523, 2014). "The levels of ox-LDL, hypersensitive C-reactive protein (hs-CRP), interleukin-1β, interleukin-6 (IL-6) and tumor necrosis factor-α (TNF-α) were measured in the plasma of 41 gout patients [28 in acute phase episode, 13 in intermittent phase (IP)], and in 40 healthy controls." (PMID 24068523, 2014). "IL-6, IL-8 or TNFα released by PBMCs was not significantly different between gout patients and controls for any of the stimuli, single or in combination." (PMID 22762240, 2012). "Furthermore, our in vitro experiments showed that MSU crystals induced IL-1, IL-6, TNF-α and RANKL, and all were found to be highly expressed in the SFMCs of patients with gouty arthritis." (PMID 21992185, 2011). "Thus, we propose that pro-resorptive cytokines, such as IL-1, IL-6, TNF-α and RANKL, contribute to osteoclastic bone resorption in patients with chronic gout." (PMID 21992185, 2011). "IL-6 is known to be raised in gout, but it had not been studied in the MSU-stimulated murine air pouch." (PMID 18522745, 2008). "TNF-α, IL-6 and PGE2 all have important roles in inflammatory arthropathies, including gout." (PMID 17612394, 2007). "The protein concentrations of inflammatory cytokines (IL-1β, TNF-α, and IL-6) significantly increased after ATG7 overexpression in MSU-stimulated THP-1 macrophages, suggesting that ATG7 may be involved in the mechanism of gout recurrence by promoting the release of inflammatory cytokines." (PMID 41221017, 2025). "Finally, dapansutrile may reduce the expression of MMP3 by regulating IL6, IL18, and IL17A, thereby degrading the extracellular matrix to treat gouty arthritis." (PMID 36105284, 2022). "Therefore, Dapansutrile may decrease the expression of MMP3 by regulating IL6, IL18, and IL17A, thereby degrading the extracellular matrix for the treatment of gouty arthritis." (PMID 36105284, 2022). "However, in a gouty arthritis animal model, SMWE more efficiently downregulated MSU-crystal-induced swelling and pain, and it exerted anti-inflammatory effects by suppressing proinflammatory cytokines (IL-1β, TNF-α, and IL-6) and MPO activity." (PMID 33535406, 2021). "In particular, some cases of gouty arthritis were reported clinically, and only one experimental study reported that BV reduces levels of NF-κB nuclear translocation, leading to the suppression of proinflammatory cytokines such as TNF-α, IL-1β, and IL-6 in MSU-induced gouty mice." (PMID 34564665, 2021). "However, in patients with gout, MSU crystals also mediate local and systemic inflammatory processes which can induce many inflammatory cytokines, including tumor necrosis factor α (TNF-α), interleukin-1β (IL-1β), interleukin-6, and interleukin-8." (PMID 25250773, 2014).
gout (continued). "Moreover, catechins exhibit potent free radical scavenging activity, significantly reducing the secretion of IL-1β and IL-6 in C57BL/6 mice induced by MSU crystals, while inhibiting the activation of the NLRP3 inflammasome, thus effectively reducing the likelihood of developing gout in patients." (PMID 37519890, 2023). "MSU crystals alone failed to induce IL-1β, IL-6 or TNFα in both patients and control groups, but a stronger synergy between MSU/Pam3Cys and MSU/C18:0 for the induction of IL-1β was found in patients with gout compared to healthy controls." (PMID 22762240, 2012).
leukocytosis (141 papers, 2008 to 2026). "Heparin reversal by protamine has been reported to cause leukocytosis, and increased levels of complement factor C5b‐9, interleukin (IL)‐6, and IL‐8." (PMID 39303134, 2024). "IL-6, an important mediator of inflammation, causes leukocytosis characterized by a rapid neutrophilia by releasing of PMN leukocytes from the bone marrow." (PMID 23509754, 2013). "In our study, metastasis in 4 T1 tumour-bearing mice was associated with substantial leukocytosis, activation of IL-6-dependent mechanisms and an acute phase response, all of which could contribute to the further acceleration of metastasis formation." (PMID 29788918, 2018). "Moreover, scorpion venoms could enhance the release of different inflammatory mediators which cause leukocytosis and raise the cytokines levels such as IL1b, IL6, IL8, IL10, TNFa and NO." (PMID 29367926, 2017). "Blocking IL-6 can result in less apparent symptoms of infection (e.g., lower fever or less pronounced leukocytosis), leading to delayed diagnosis and potentially higher severity of the infection." (PMID 41357870, 2025). "CRP rises proportionally to IL-6-mediated hepatocyte stimulation and mirrors both systemic and local biliary inflammation more directly than leukocytosis or cholestatic indices." (PMID 40786322, 2025). "Studies show that KDSS patients often display neutrophilia, leukocytosis, elevated cytokine levels (IL-6, IL-10), hypoalbuminemia, and IVIG resistance, features that align with exaggerated systemic inflammation rather than a fundamentally different phenotype." (PMID 41204570, 2025). "Limitations of inflammatory markers: the disease worsened although the patient’s leukocytosis and IL-6 levels improved markedly during treatment, highlighting that relying solely on blood tests is insufficient to determine treatment efficacy." (PMID 40324246, 2025). "Abdominal adipose tissue secretes a variety of inflammatory factors, such as tumor necrosis factor and interleukin-6, which can stimulate the immune system and lead to leukocytosis." (PMID 40115939, 2025). "IL‐10 showed negative correlations with the rest inflammatory markers on the 3rd day (WBC, CRP, ESR, ANC, NLR, and IL‐6), suggesting attenuating effect on IL‐6 levels, but also possible effect on leukocytosis reduction (by decreasing WBC, ANC, and NLR)." (PMID 35762501, 2023). "Changes in sleep patterns can cause leukocytosis and an increase in natural killer cells, as well as an increase in inflammatory cytokine production, such as TNF and IL6." (PMID 37663979, 2023). "Analysis of BALF revealed reduction in oxidative stress markers, IL-6 level, leukocytosis and neutrophilia." (PMID 35945895, 2022). "Leukocytosis is a well-known paraneoplastic syndrome in dogs, in which expression of G-CSF and GN-CSF, as well as IL-6, has been reported to be increased." (PMID 36136714, 2022). "One LD50 injection in mice produced a severe envenomation state, with a significant reduction of the complement activity, leukocytosis, neutrophilia, monocytosis, and strong systemic production of IL-6, CCL2, and TNF-α." (PMID 33936074, 2021). "In a previous study, patients with COPD included higher proportions of smokers with elevated CRP, leukocytosis, interleukin (IL)-6, and tumor necrosis factor (TNF)-α levels when compared to patients without COPD." (PMID 34537026, 2021). "One bout of high-intensity and prolonged exercise is known to induce acute leukocytosis and increase concentrations of cytokines such as IL-6 and IL-10 in the serum." (PMID 33139757, 2020). "The LPS + PM group showed persistent inflammation characterized by BALF leukocytosis, increased IL-1β and IL-6 levels in the lung parenchyma, decreased alveolar air space volume, septal thickening and decreased septa surface density." (PMID 32943719, 2020). "Marked leukocytosis and increase in D-dimer, C-reactive protein, IL-6, and procalcitonin levels developed." (PMID 32607684, 2020).
leukocytosis (continued). "CPB induced leukocytosis with increased plasma levels of tumor necrosis factor-α and interleukin-6 indicating a potent inflammatory response." (PMID 29593559, 2018). "In many IRAK-4-deficient patients clinical and laboratory signs of inflammation (such as CRP, IL-6, leukocytosis) develop slowly even in instances of severe infection, as seen in the first sibling in our study." (PMID 24625087, 2014). "WBC counts are elevated in ATC in part because some ATC cells produce several growth factors and cytokines, such as colony-stimulating factor (CSF), interleukin-1α (IL-1α), IL-3, and IL-6, which lead to leukocytosis." (PMID 24224029, 2013). "In healthy subjects, a single exercise session results in immune cell activation, which is characterized by production of immune modulatory peptides (e.g. IL-6, IL-8), a leukocytosis and enhanced immune cell functions." (PMID 23497303, 2013). "Both TNF-α and IL-6 have been shown to decrease with long-term physical activity resulting in significant decreases in leukocytosis and neutrophilia." (PMID 22363616, 2012). "IL-1β is among the earliest cytokines activated after UV exposure; it induces vasodilation, fever, and leukocytosis, stimulates IL-6 production, and activates matrix metalloproteinase (MMPs) expression, contributing to photoaging and extracellular matrix degradation." (PMID 41596382, 2026). "In summary, the results of this study demonstrate that the 2000-m rowing ergometer test induces a physiological inflammatory response (as indicated by increased IL-6) and immune activation (as indicated by leukocytosis), while maintaining efficient recovery mechanisms." (PMID 40873756, 2025). "Furthermore, the existence of CE is not predicted by peripheral blood inflammation markers such C-reactive protein (CRP), leukocytosis, leptin, and IL6." (PMID 39941173, 2025). "It was suggested that the leukocytosis could represent a systemic inflammatory response induced by IL-6 secreted from the pheochromocytoma." (PMID 41477390, 2025). "Interestingly, plasma levels of Gas6 in RA patients have been reported to positively correlate with disease activity scores (DAS-28), erythrocyte sedimentation rate (ESR), leukocytosis, and IL-6." (PMID 37242486, 2023). "Janus tyrosine kinase (JAK)-STAT3 signaling dysregulation promotes leukocytosis via IL-6." (PMID 37041610, 2023). "The exercise-dependent systemic inflammatory response that we observed immediately after a soccer game encompassed both strenuous physical activity–induced transient leukocytosis as well as increases in circulating IL-6 and TNF α, early mediators of exercise-induced inflammation." (PMID 32879387, 2020). "Neutrophilia with moderate leukocytosis observed in this study after mixture administration could be the result of neutrophil release and mobilization under inflammatory IL-6 and TNF-α from marginal neutrophil pools." (PMID 30669347, 2019). "Even though inflammation starts as a local reaction, it associates a systemic acute phase response that involves pro-inflammatory mediators (IL-6; IL-1β; TNF-α), bone marrow response causing leukocytosis, liver response with acute phase proteins (APPs) synthesis." (PMID 31664997, 2019). "Oral glycine and Pro‐Hyp attenuated the recruitment of inflammatory cells into the colonic tissue, possibly owning to their prevention of leukocytosis and lymphocytosis, and this may explain their effectiveness in suppressing the colonic increase in IL‐6 and TNF‐α." (PMID 29983966, 2018). "In addition, some patients displayed marked leukocytosis and IL-6 and TNF-α production in plasma." (PMID 28379166, 2017). "However, cancer has been shown to produce myeloid growth factors, such as granulocyte colony-stimulating factor, tumor necrosis factor-alpha, interleukin-1, and interleukin-6, which may influence tumor-related leukocytosis and neutrophilia." (PMID 24089602, 2013).
leukocytosis (continued). "Hematologic (June 3, 2024): Leukocytosis (white blood cells [WBC] 34.41 × 109/L), neutrophils 85%, and markedly elevated IL-6 (6129.94 pg/mL), indicative of systemic inflammation." (PMID 40324246, 2025). "Common indicators of this early response include leukocytosis, C-reactive protein (CRP), and interleukin-6 (IL-6) providing rapid defense against viral intrusion." (PMID 40076968, 2025). "Severe cases exhibited marked leukocytosis (median 8.12 × 109 L−1, IQR 7.00–11.82 vs. 5.96 × 109 L−1, 4.18–8.53; p = 0.003) and an almost five-fold higher IL-6 concentration (18 pg mL−1, 6–25 vs. 4 pg mL−1, 2–7; p < 0.001)." (PMID 40872832, 2025). "Follow-up blood tests on June 9, 2024, showed improved leukocytosis (WBC: 13.38 × 109/L) and IL-6 (678.52 pg/mL)." (PMID 40324246, 2025). "IL-6, a pyrogen similar to IL-1 and TNF-α, mediated the acute phase response characterized by leukocytosis and increased acute phase reactants." (PMID 37628768, 2023). "The rAcH3.3 instillation also increased apoptotic activity (cleavage of caspase 3 and 9) and triggered acute systemic inflammatory marker activation (TNF-α, IL-6, MCP-3, or CXCL-1) in plasma, accompanied by leukocytosis and lymphocytosis." (PMID 37759735, 2023). "Mann-Whitney test showed that there was a significant difference between IL-6 levels in the LOS, oxygen saturation, leukopenia/leukocytosis, AKI, and ARDS (p 0.05)." (PMID 37889917, 2023). "Previous studies have shown that acute short-term exercise can trigger a pro-inflammatory effect presented by elevated secretion of IL-6 and CRP, and to a lesser extent, TNF-α levels, in addition to triggering leukocytosis and oxidative stress." (PMID 36504710, 2022). "Patients with leukocytosis significantly decreased complement levels, while the TGF-β and IL-6 significantly increased in patients with high creatinine levels and higher ESR." (PMID 36397759, 2022). "Laboratory tests performed at admission showed marked leukocytosis (WBC count, 34,900/μL; neutrophils, 97%) and elevated levels of CRP (8.4 mg/dL), G-CSF (452 pg/mL), and interleukin-6 (IL-6; 81.4 pg/mL)." (PMID 34021462, 2021). "Another group of factors intensifying exercise leukocytosis is secreted cytokines (TNF, IL-1, IL-6)." (PMID 33802129, 2021). "Leukocytosis following exercise is a well-described stress/inflammatory activation phenomenon in healthy humans: our data showed that leukocytosis after triathlon competition was coincident with the increase of the inflammatory cytokines TNF-α and IL-6." (PMID 32256948, 2020). "LPS-induced rats showed significant leukocytosis, and elevated serum levels of CRP, TNF-α, IL-1β, IL-6, IL-8, MCP-1, malondialdehyde (MDA) and 8-hydroxy-2′-deoxyguanosine (8-OHdG), accompanied with diminished antioxidants." (PMID 30858869, 2019). "In conclusion, we showed that mammary ASR, which manifested itself by an intense milk leukocytosis, was characterized by the production of IL-17A and IFN-γ but the absence of detectable TNF-α, with a low and inconsistent presence of IL-1β and IL-6." (PMID 23696826, 2013). "IL-7 promotes leukocytosis by inducing proliferation of lymphocytes; it also increases WBC by stimulating secretion of IL-1, IL-6, and tumor necrosis (TNF) factor from circulating lymphocytes, monocytes, and macrophages." (PMID 22844297, 2012). "The nonspecific immunological response was gauged using interleukin 6, leukocytosis, and C-reactive protein." (PMID 40076968, 2025). "Despite the patient’s leukocytosis (WBC: 13.38 × 109/L) and IL-6 levels (678.52 pg/mL) decreasing significantly on June 9, 2024, from initial levels (WBC: 34.41 × 109/L; IL-6: 6129.94 pg/mL) on June 3, the disease worsened, emphasizing that relying solely on blood tests isn’t enough." (PMID 40324246, 2025). "Concomitant changes in MMP-9 or YKL-40 may suggest remodeling or ongoing inflammation, yet most of the markers of acute inflammation (IL-6 and IL-8) resolved, while others persevered (CRP, leukocytosis)." (PMID 36271425, 2022).
leukocytosis (continued). "There was also a positive correlation between the WBC, neutrophil an IG count, neutrophil and IG percentages, leukocytosis, neutrophilia, NLR, and IL-6 levels and the need for MV and ICU treatment, and a negative correlation between the lymphocyte percentage and the need for MV and ICU treatment." (PMID 36016322, 2022). "Our results reproduced these findings, since leukocytosis and an increase in both IL-6 and IL-10 post-race was found regardless of LPS stimulation." (PMID 33139757, 2020). "Furthermore, the animals demonstrated leukocytosis characterized by neutrophilia and monocytosis, as well as increased plasma levels of MCP-1 and IL-6." (PMID 30657756, 2019). "In addition to amelioration of leukocytosis, SBH reduced the circulating levels of inflammatory mediators, including CRP, MCP-1, TNF-α, IL-1β and IL-6 in LPS-induced rats." (PMID 30858869, 2019). "On laboratory data, leukocytosis is often present, rarely due to eosinophilia, there could be also a nonspecific elevation of lactic dehydrogenase or serum IL-6, a mucin like glycoprotein expressed on type II pneumocytes and bronchiolar cells." (PMID 33331164, 2021). "First, although we had previously reported that a high DII diet before pregnancy is associated with leukocytosis in the first trimester, we did not measure plasma inflammatory markers, such as white blood cell, cytokines, such as CRP, IL-6, and TNFα, at the time of delivery in the present study." (PMID 33202775, 2020). "In a typical inflammatory response model, interleukin-6 (IL-6) and tumor necrosis factor-alpha (TNF-α) are produced first, followed by an increase in interleukin-2 (IL-2) and interleukin-1α (IL-1α), which may lead to leukocytosis due to neutrophilia in the systemic circulation and immunosuppression." (PMID 38918542, 2024). "Regarding nonspecific immunological responses, leukocytosis, CRP, or serum levels of IL-6 or procalcitonin at admission were not a differentiating factor." (PMID 40076968, 2025). "It was found that the levels of IL-1β, IL-6, and ICL were significantly higher in patients with high leukocyte counts and signs of inflammation compared with patients who had no leukocytosis." (PMID 34795992, 2021). "It was found that in patients with positive viral DNA results and a low leukocyte count, the levels of IL-1β, IL-6, ICL, IFN-α, IFN-γ, and CD8 were significantly lower compared with children with negative viral DNA tests and persistent leukocytosis." (PMID 34795992, 2021).